NGF (nerve growth factor)
Diseases named in the same sentence as NGF in open-access papers (continued):
Sharing a sentence is not in itself a finding about the gene and the disease.
refractive error (1 paper, 2025). A defect in the focusing of light on the retina as in astigmatism, myopia, or hyperopia. "Since not all high-myopic eyes develop mCNV, implying the existence of some neuroprotective mechanisms, we hypothesized the participation of NGF and BDNF as well as few oxidative-related and epigenetic factors in the progression of this refractive error." (PMID 40650128, 2025).
renal fibrosis (1 paper, 2023). A final common manifestation of a wide variety of chronic kidney diseases characterized by glomerulosclerosis and tubulointerstitial fibrosis. "For instance, single-cell RNA sequencing in a mouse model of renal fibrosis demonstrated an unexpected upregulation of NGF." (PMID 37711613, 2023).
Renal insufficiency (1 paper, 2013). A reduction in the level of performance of the kidneys in areas of function comprising the concentration of urine, removal of wastes, the maintenance of electrolyte balance, homeostasis of blood pressure, and calcium metabolism. "Moreover, a link between renal involvement and enhanced NGF levels has been described in SLE mice and in patients with SLE glomeronephritis-related renal insufficiency, which could explain this discrepancy." (PMID 24223945, 2013).
rosacea (1 paper, 2024). A chronic erythematous skin disorder that affects the face. "Rosacea is associated with a microbiome dysbiosis with increase in Demodex mites and expression of transient receptor potential cation channel subfamily V member 1 TRPV1, tropomyosin receptor kinase A (TrkA) and nerve growth factor (NGF), triggering cutaneous neurogenic inflammation." (PMID 38899754, 2024).
secondary hyperparathyroidism (1 paper, 2013). Overproduction of parathyroid hormone in response to influence external to the parathyroid glands. "Vitamin D might affect cognition at least partly independent of AChE and BuChE involving L-type voltage-sensitive calcium channels, nerve growth factor, prostaglandins, cyclooxygenase 2, reactive oxygen species, nitric oxide synthase, and prevention of secondary hyperparathyroidism." (PMID 24312390, 2013).
seminoma (1 paper, 2021). A radiosensitive malignant germ cell tumor found in the testis (especially undescended), and extragonadal sites (anterior mediastinum and pineal gland). "Nuclear overexpression of p75NTR was detected by immunohistochemistry in seminoma tissue as compared to normal tissue, whereas neither NGF nor its high-affinity TrkA receptor was detected." (PMID 34209730, 2021). "The same immunopositivity pattern for p75NTR was observed only in 4/14 of non-seminoma samples; all samples were immunonegative for NGF and TrkA (data not shown)." (PMID 34209730, 2021).
skin aging (1 paper, 2021). The gradual irreversible changes in structure of skin that occur as a result of the passage of time.. "TF ETS1, which was regulated through the signaling pathway activated by ligand NGF, has been identified to be associate with skin aging." (PMID 34073305, 2021).
skin cutaneous melanoma (1 paper, 2022). "Gene expression analysis of NGF performed with GEPIA revealed a wide range of mRNA expression in both skin cutaneous melanoma (SKCM) and normal skin tissue." (PMID 35457078, 2022).
skin sensitization (1 paper, 2021). An immunological response to previous exposure to a substance which results in an inflammatory skin reaction. "In the established NGF model of human skin sensitization, we investigated if BAM8–22-, β-ALA- or ET-1-induced itch sensations were altered following rhNGF injections." (PMID 34728705, 2021). "Herein, we therefore tested whether experimental NGF-induced skin sensitization of healthy volunteers produces a generalized sensitization to non-histaminergic pruritogens in parallel to thermal (day 3) or mechanical (day 21) hyperalgesia." (PMID 34728705, 2021).
small cell carcinoma (1 paper, 2018). A neuroendocrine carcinoma composed of small malignant cells which are often said to resemble "oat cells" under the microscope. "Small cell cancers displayed a lower level of NGF staining compared to other cancer subtypes (h-score 54) (p < 0.0001)." (PMID 29802376, 2018).
spinal cord disorder (1 paper, 2016). A disease involving the spinal cord. "Therefore, we hypothesize that CRP and NGF are measurable in serum and urine samples and can be used as biomarkers in either serum or urine to distinguish between micturition disorders caused by neurologic dysfunctions or bacterial cystitis in dogs with spinal cord disease." (PMID 26746899, 2016). "The purpose of this study was to prove the hypothesis that C-reactive protein (CRP) and nerve growth factor (NGF) may be potential biomarkers for lower urinary tract disorders and may be able to distinguish between micturition dysfunctions of different origin in dogs with spinal cord diseases." (PMID 26746899, 2016). "From these data we conclude that neither CRP nor NGF in urine or serum can be considered as reliable biomarkers for micturition disorders in dogs with spinal cord disorders in a clinical setting, but their production might be part of the pathogenesis of such disorders." (PMID 26746899, 2016).
spinal cord ischemia (1 paper, 2020). Reduced blood flow to the spinal cord which is supplied by the anterior spinal artery and the paired posterior spinal arteries. "Studies have shown that the application of corresponding treatments after spinal cord ischemia can induce NGF to activate the PI3K–Akt pathway to inhibit neuronal apoptosis." (PMID 32630523, 2020).
spinal stenosis (1 paper, 2022). Narrowing of the spinal canal. "Radiologic grading of FJOA and spinal stenosis, followed by immunohistochemistry for NGF, TrkA and SP on consecutive tissue sections, was performed in ten specimens." (PMID 35300334, 2022). "This cross-sectional study using a small sample size of primarily end-stage FJOA samples from lumbar spinal stenosis patients revealed abundant NGF expression in damaged cartilaginous tissue." (PMID 35300334, 2022). "Here we identified predominant NGF and SP expression in damaged cartilaginous tissue of osteoarthritic lumbar facet joints from patients with spinal stenosis." (PMID 35300334, 2022). "In addition, we investigated whether NGF tissue expression was associated with radiological severity of FJOA and lumbar spinal stenosis." (PMID 35300334, 2022).
status epilepticus (1 paper, 2020). Status epilepticus is defined as a continuous seizure lasting more than 30 min, or two or more seizures without full recovery of consciousness between any of them. "Several studies have demonstrated that neurotrophic factors, including NGF and BDNF, are elevated after status epilepticus, which promotes the survival of neurons post-seizure." (PMID 33177978, 2020).
systemic amyloidosis (1 paper, 2020). "B2M is responsible for systemic amyloidosis, which can dysregulate the levels of BDNF and NGF." (PMID 32059688, 2020).
systemic mastocytosis (1 paper, 2017). Systemic mastocytosis (SM) comprises a heterogeneous group of rare acquired and chronic hematological malignancies that are related to an abnormal proliferation of mast cells in tissue, including bone marrow, with or without skin involvement. "In this study, we demonstrate that activation of TRKA by its ligand nerve growth factor (NGF) is potent to trigger a disease in mice with striking similarities to human systemic mastocytosis (SM)." (PMID 29088753, 2017).
tetanus (1 paper, 2016). A serious infectious disorder that follows wound contamination by the Gram-positive bacterium Clostridium tetani. "Tetanus neurotoxins can bind to various types of cells, including the NGF-treated neuronal-like PC-12 cells through the Hc domain." (PMID 27626445, 2016).
tic disorder (1 paper, 2018). Disorders characterized by recurrent TICS that may interfere with speech and other activities. "The purpose of this study was to compare serum GDNF and NGF levels, demographic characteristics and clinical parameters between in patients with tic disorder and healthy controls." (PMID 30190739, 2018). "The aim of this study was to investigate serum Glial Cell Line-Derived Neurotrophic Factor (GDNF) and Nerve Growth Factor (NGF) levels in patients with tic disorder and healthy controls." (PMID 30190739, 2018). "Serum NGF and GDNF levels were higher in females with tic disorder than males in our study." (PMID 30190739, 2018). "Our study was perhaps the first study to investigate serum NGF and GDNF levels in tic disorder." (PMID 30190739, 2018). "Serum NGF and GDNF levels were higher in females with tic disorder than males." (PMID 30190739, 2018). "The fact that NGF and GDNF levels were not correlated with tic disorders in our study does not exclude the role of neurotrophic factors in the etiopathogenesis of tic disorder." (PMID 30190739, 2018).
tongue tumors (1 paper, 2024).
tuberculoid leprosy (1 paper, 2018). A principal or polar form of leprosy in which the skin lesions are few and are sharply demarcated. "Studies have shown that different levels of NGF are associated with lepromatous and tuberculoid leprosy such that higher levels of NGF are associated with lepromatous forms and low levels of NGF are associated with tuberculoid forms of the disease." (PMID 29867937, 2018).
tuberous sclerosis (1 paper, 2025). Hereditary disease characterized by seizures, intellectual disability, developmental delay, and skin and ocular lesions. "Elevated NGF in tuberous sclerosis and postinfectious ISs has led to the hypothesis that excessive NGF may actively promote hyperexcitability and could represent a future therapeutic target in these subtypes." (PMID 41470225, 2025).
urinary tract infection (1 paper, 2023). "Nevertheless, it’s imperative to note that urinary NGF levels also surge in cases of urinary tract infections, bladder outlet obstruction, and urinary calculi." (PMID 37940904, 2023).
varicocele (1 paper, 2023). A condition characterized by the dilated tortuous veins of the spermatic cord with a marked left-sided predominance. "The correlation between the NGF level and motile and live sperm in men with varicocele was less evident; however, this group showed a high NGF level and, as expected, a high level of immature sperm." (PMID 38137566, 2023). "NGF was significantly higher in men with varicocele or UGI compared with fertile men (2049.0 ± 750.8 pg/mL and 1673.0 ± 457.6 pg/mL vs. 763.3 ± 279.4 pg/mL; p = 0.015 and p = 0.02, respectively (image on the left)." (PMID 38137566, 2023). "On the contrary, a NGF level that is too high could be considered a determinant for dysfunction, as shown in men with varicocele and UGIs, who presented an NGF level of 1244 pg/mL and 3260 pg/mL, respectively." (PMID 38137566, 2023). "In this paper, we aimed to evaluate the distribution and the role of NGF and its receptors (p75NTR and TrKA) on the reproductive apparatus (testis and epididymis) and sperm of fertile men (F) and men with different pathologies, namely varicocele (V) and urogenital infections (UGIs)." (PMID 38137566, 2023). "There was not a significant difference in the NGF level between men with varicocele and men with UGIs (p = 0.4)." (PMID 38137566, 2023).
vascular insufficiency (1 paper, 2012). "Also, this study has examined whether NGF is engaged in the role of sensory nerves’ ASIC3 in augmented responses evoked by the hindlimb vascular insufficiency." (PMID 22934005, 2012).
Visual impairment (1 paper, 2021). "Recent studies have demonstrated that the administration of exogenous Nerve Growth Factor (NGF) as eye-drops, either in children or adults with severe visual impairment due to low-grade OGs, is associated with a significant improvement of both the visual evoked potential and the ocular function." (PMID 34257579, 2021).
vitamin A deficiency (1 paper, 2020). Deficiency of vitamin A due to malnutrition, malabsorption, or dietary lack. "Vitamin A deficiency decreases maintenance levels of nerve growth factor (NGF) and brain-derived neurotrophic factor (BDNF), which ordinarily protect the retina from oxidative stress injury and stimulate repair." (PMID 32582807, 2020).
vitiligo (1 paper, 2025). Generalized well circumscribed patches of leukoderma that are generally distributed over symmetric body locations and is due to autoimmune destruction of melanocytes. "Additionally, multiple studies found that Stress-induced neuropeptide release, elevated nerve growth factor (NGF), and catecholamine metabolite levels may suggest an important role for the neural factors in vitiligo development." (PMID 40709998, 2025).
tumor (374 papers, 1995 to 2026). "Clinical studies demonstrate that NGF expression is associated with cancer‐associated neuroplasticity and advanced tumor grade." (PMID 41556039, 2026). "In contrast, NGF, associated with pro-tumoral effects, was expressed in tumor spheres and tumor-like cells, with lower expression in assembloids." (PMID 40917877, 2025). "The long half-life of NGF in blood and tumor was found to be associated with serum binding by SDS-PAGE analysis." (PMID 40048021, 2025). "For some patients with advanced tumours, tumour-derived NGF causes bone tissue remodelling, aggravating local bone pain and pathological fracture." (PMID 40783715, 2025). "The ability of NGF to precisely locate and retain in tumor tissue offers substantial groundwork for future diagnostic and therapeutic applications." (PMID 40048021, 2025). "In primary and secondary tumours of bone, tumour cells can induce sensory and sympathetic nerve endings to grow into the tumour tissue via the nerve growth factor-TrkA signalling pathway, leading to cancer-associated osteodynia." (PMID 40860871, 2025). "Axonal attraction in the OS TME, likely driven by tumour-associated stroma, appears to be mediated by neurotrophic factors such as NGF and BDNF, key regulators of neuronal survival, differentiation, and outgrowth during nerve regeneration." (PMID 41029717, 2025). "Increased expression of NGF and its receptors in tumor cells is associated with a greater frequency and severity of PNI." (PMID 40421086, 2025). "Preclinical studies have demonstrated the efficacy of NGF inhibitors and TrkA antagonists in reducing neural density, impairing tumor growth, and alleviating cancer-associated pain." (PMID 41009819, 2025). "NGF, released by cancer cells, tumor-associated immune cells, and fibroblasts, stimulates the sensitive sensory nerves by interacting with transient receptor potential cation channel subfamily V member 1 (TRPV1)." (PMID 39723256, 2024). "NGF blockade can decrease nociception, restrict tumor proliferation, and reduce weight loss by leptin and pro-inflammatory cytokines production." (PMID 39099944, 2024). "In gastric epithelium, cholinergic stimulation induces NGF production, promoting tumor formation and growth via the M3 receptor and Yes‐associated protein pathways." (PMID 39492832, 2024). "The inhibition of nerve growth factor (NGF) serves as a crucial approach to hinder the advancement of diseases by impeding the growth and restructuring of neural fibers linked to the tumor." (PMID 38089966, 2023). "Numerous studies have shown that high level of NGF in PC are closely associated with tumor cell migration and perineural invasion." (PMID 36285300, 2022). "Infiltration of the tumor microenvironment by nerve fibers involves NGF production by BC cells and is associated with BC aggressiveness." (PMID 34268306, 2021). "In the context of cancer, the activation of NGF‐TrkA signaling axis is an important step to produce IL‐10 in tumor‐associated macrophages (TAMs)." (PMID 34542930, 2021). "In consideration of the complexity and variety of signal pathways involved in the tumour microenvironment, the mechanism underlying NGF/TrkA function on EMT and proliferation between PSCs and PC cells still needs further study." (PMID 32294802, 2020). "The NGF gene encodes a growth factor that can be released into or produced by the tumor microenvironment." (PMID 32508884, 2020). "Rita Levi-Montalcini discovered that tumor extracts can cause neurite outgrowth and identified the factor as the nerve growth factor (NGF)." (PMID 31277491, 2019). "In line with this, anti-NGF based therapies have been demonstrated to be a promising approach in tumor treatment, as well as in tumor associated cancer pain." (PMID 31812953, 2019). "Brain-derived neurotrophic factor and nerve growth factor are both neurotrophins linked to tumor development, promoting proliferation, angiogenesis, and invasion." (PMID 30245591, 2018).